PMS2 (PMS1 homolog 2, mismatch repair system component)
Diseases named in the same sentence as PMS2 in open-access papers (continued):
Sharing a sentence is not in itself a finding about the gene and the disease.
cancer (continued). "In prostate, defects of PMS2 in cancer cell lines have been documented in prior studies." (PMID 26036629, 2015). "This could indicate selection of sub-clones for which epigenetically reduced expression of Pms2, Ercc1 and/or Xpf was reversed under the new micro-environment of a growing cancer." (PMID 22494821, 2012). "Controversies exist regarding the mechanism through which PMS2 and PMS1 may act to predispose towards cancer." (PMID 19466295, 2009). "Moreover, many pathogenic PMS2 variants are expected not to manifest any cancer phenotype over the course of individual’s lifetime." (PMID 41333974, 2025). "On the other hand, variants in PMS2 did not confer a significant risk of cancer." (PMID 37864171, 2023). "Having analyzed the prevalence of pathogenic/likely pathogenic germline variants in cancer-predisposition genes in 334 HCC patients considered for liver transplantation, we found only 7/334 (2.1%) carriers of pathogenic variants in established cancer-predisposition genes (PMS2, 4×NBN, FH or RET)." (PMID 36612198, 2022). "An interesting still remaining question is whether or not cancers with multiple HRR mutations as our MLH1-/PMS2-/MSH6- cases are more likely to benefit from PARP-inhibitor therapy than those with only a single HRR mutation." (PMID 36387226, 2022). "However, some of our observed mutations have not been linked to dMMR CRCs yet and we could detect up to six synchronous MMR/HRR mutations in our MLH1-/PMS2-/MSH6- cases, which is something we rarely observe in clinical practice in other cancer entities." (PMID 36387226, 2022). "In the integrated germline and somatic assessment presented here, germline variants in MSH6 and PMS2 were assessed with the combination of MMR/MSI/IHC/LOH and personal clinical findings, all of which collectively elucidate a likely involvement of the germline variant in patient cancer." (PMID 36091175, 2022).
cancer (continued). "No cancer was detected in patients with MSH6 or PMS2 mutations." (PMID 33916129, 2021). "Two of these cancers were negative for MLH1/PMS2 and one showed isolated protein loss of MSH6." (PMID 32144630, 2020). "Interestingly, abrogation of other components of the DDR, such as p21, Pms2 and Exo-1, can rescue survival of Terc-deficient mice without increasing cancer." (PMID 24920220, 2014). "Thus, it appears that a field defect comprising about 1 million crypts, with most crypts expressing reduced protein levels of Pms2 and Ercc1, but high levels of Ku86, surrounds the cancers of these patients, and likely similar field defects surround TVAs as well." (PMID 22494821, 2012). "Specifically, three BC patients with a personal/family history of LS-related cancers were found to be carriers of two PVs in MLH1 and one PV in PMS2, respectively." (PMID 40361347, 2025). "The other ST, a carcinoma with strong punctate (equivocal) MLH1 staining, showed equivocal PMS2 staining." (PMID 39847610, 2025). "Overexpression of the PMS2 gene disrupts MMR function, establishing an additional carcinogenic mechanism leading to genetic instability and resistance to cytotoxic cancer therapy." (PMID 38714954, 2024).
cancer (continued). "PMS2 variants have low cancer penetrance; family histories may thus be absent." (PMID 36647049, 2023). "Together, these findings strongly suggest that the interplay of this POLD1 variant, likely to impair the proofreading function of POL δ, and the heterozygous PMS2 PV is responsible for the siblings’ AYA colorectal and other cancers." (PMID 36291559, 2022). "We found that 11.5% (3/26) of driver genes including PMS2, CDKN2A and TERT are significant in the prognosis at least two cancer types." (PMID 35962343, 2022).
cancer (continued). "The heatmap results showed that GNL3L was only positively correlated with PMS2 in UCS, which co-expressed and significantly correlated with at least two of these genes in the remaining cancers." (PMID 36230520, 2022). "This pathway is a genetic disease about DNA repair genes–BRCA1, RAD51, PMS2 and FANC proteins–which are higly related to cancers." (PMID 27883053, 2016). "Notably, 10 rare PMS2 truncations were found in the validation set, with 4 from UCEC, 2 each from LUAD and LUSC and 1 each from BRCA and PRAD; these observations confirm the significance of PMS2 in susceptibility and broaden its role in cancer types not previously implicated." (PMID 26689913, 2015). "Onset of CRC is later for MSH6, with few or no cancers detected before 30–35 years of age, and the risk of CRC in PMS2 PV carriers before 50 years of age is negligible if undergoing active colonoscopy surveillance." (PMID 37165697, 2023).
cancer (continued). "In view of the low penetrance of PMS2 PVs and its presence in the germlines of their mother and brother who do not have cancer, it was deemed unlikely that heterozygosity for this PMS2 PV was alone responsible for the teenage onset of CRC in both siblings." (PMID 36291559, 2022). "Considering the high incidence of cancers arising in the digestive system and the frequency of 1.4% of MLH1-/PMS2-/MSH6- cases across the included entities, a considerable number of patients could fall into this subgroup overall." (PMID 36387226, 2022). "Removing part of the colon or rectum in the absence of cancer or endoscopically non‐removable polyps is not generally recommended for path_MSH6 and path_PMS2 carriers." (PMID 34043773, 2021). "We observed that in carriers of PMS2 c.989-1G > T 83% of cancers included in the AMS1/AMS2/Bethesda clinical criteria had normal expression of PMS2." (PMID 24790682, 2014). "Similarly to cancer tissues, in adjacent mucosal tissues, MLH3 correlated with PMS1 and PMS2 (R = 0.887 and R = 0.931, P < 0.000, respectively), but, additionally, MLH3 also correlated with MSH6 (R = 0.857, P < 0.0001)." (PMID 24484585, 2014).